TRBV1 (T cell receptor beta variable 1 (pseudogene))
Synonyms: TCRBV27S1P; TCRBV1S1P
Gene: T-cell receptor variable (V) pseudogene on chromosome 7 (142,299,177 to 142,299,460, forward strand). Ensembl gene ENSG00000242736.
Diseases named in the same sentence as TRBV1 in open-access papers:
TRBV1 is named in the same sentence as 8 diseases in open-access papers, as found by Europe PMC text mining. Sharing a sentence is not in itself a finding about the gene and the disease. The quoted sentences say what the papers report.
atherosclerosis (1 paper, 2025). A disease characterized by the build-up of fatty material and calcium deposition in the arterial wall resulting in partial or complete occlusion of the arterial lumen. "Additionally, Trbv1 was associated with reactive arthritis [S23] and myeloperoxidase‐induced autoimmunity [S24], and Trbv31 was linked to atherosclerosis [S25]." (PMID 40665793, 2025).
Sjögren's syndrome (1 paper, 2025). "For the β chain, many V/J genes, which were highly expressed in cachexic HCC mice, were associated with type I diabetes, such as Trbv1 [S18,19], Trbv13‐2 [S19], Trbj2‐7 [S19,20] and with Sjögren's syndrome, such as Trbv3 [S21], Trbv16 [S22] and Trbj2‐2 [S22]." (PMID 40665793, 2025).
viral infection (1 paper, 2020). "Quantifying the percent of unique clones aligning to each V-gene revealed a substantial (>40% of unique clones) portion of the unsorted blood repertoire consisted of TRBV1 and TRBV31 before viral infection." (PMID 32547546, 2020).
infection (1 paper, 2025). The state of being infected such as from the introduction of a foreign agent such as serum, vaccine, antigenic substance or organism. "Infection with ALV-J did not induce any changes in the TRBJ gene usage in the M-line chickens, although an increased usage of TRBV1 and a decreased usage of TRBV2 were observed compared to the control M-line." (PMID 39943104, 2025).
TRBV1 also shares sentences with these, for which no sentence is quoted: Autoimmunity (1 paper); COVID-19 (1); reactive arthritis (1); type I diabetes (1).